AR (androgen receptor)
Diseases named in the same sentence as AR in open-access papers (continued):
Sharing a sentence is not in itself a finding about the gene and the disease.
prostate carcinoma (continued). "Aberrant expression of acetyltransferases and their deregulated activities have been found to interfere with AR signaling and play a key role in development and progression of prostatic diseases, including prostate cancer (PCa)." (PMID 36060957, 2022). "NRs such as AR and ER participate in various important physiological progress in the body, and are closely related to prostate cancer and breast cancer." (PMID 36536188, 2022). "This transcription factor is also amplified in prostate cancer, where it colocalizes with and regulates AR." (PMID 35774123, 2022). "Androgen receptor pathway inhibitors (ARPIs) such as abiraterone and enzalutamide have been shown to prolong survival in patients with advanced prostate cancer." (PMID 35510101, 2022). "In prostate cancer, the AR has been shown to regulate a transcriptional profile that promotes tumour growth." (PMID 36560732, 2022). "TNF signaling has been described as pro-tumorigenic in AR-low prostate cancer, and we confirmed that TNF activity was inversely associated with AR activity in human patients." (PMID 36511483, 2022). "Prostate cancers (PCa) are distinctively sensitive to the transcriptional activity of the androgen receptor (AR) during tumorigenesis and in response to hormone-based therapies for advanced disease." (PMID 36181613, 2022). "Together, these results support our data that the targeting of p300 and CBP as a means of blocking ac-AR signaling is beneficial in prostate cancer; however, inhibition of HDACs is likely to promote AR acetylation, proving to be counter-effective for patients." (PMID 35704598, 2022). "The synthesis of N-Myc/AR/EZH2-PRC2 complex is notably dependent on the presence of EZH2, and N-MYC shows a remarkable synergistic effect with EZH2 and AR to inhibit AR signaling by methylation, leading to neuroendocrine transformation of prostate cancer." (PMID 35633416, 2022). "Another multi-institutional clinical trial also reported cases of retained AR expression and activity in prostate cancer with neuroendocrine differentiation, supporting the clinical value of further investigation in these AR/NE double-positive prostate cancer." (PMID 36033483, 2022). "Biclutamide, a well-known AR inhibitor often used to treat AR+ prostate cancer, was shown to increase PFS in AR+ TNBC in a phase II clinical trial." (PMID 35158750, 2022). "The AR-independent cells were two to four times more sensitive to FL than the AR-dependent cells, supporting the idea that prostate cancer cells become dependent on CS after ARPI." (PMID 35963852, 2022). "The majority of prostate cancer cells are dependent on androgens and activation of AR for growth and survival, and ADT remains the mainstay of treatment for advanced PCa patients." (PMID 35172032, 2022). "Prostate cancer is an endocrine-related cancer, and the AR signaling pathway, which participates in the entire disease process, is indispensable for cancer growth and distant metastasis." (PMID 36446767, 2022). "Androgen‐deprivation therapy (ADT) and androgen receptor (AR)‐targeted therapies have significantly improved outcomes for patients suffering from advanced prostate cancer (PCa)." (PMID 35014179, 2022). "AR-independent prostate cancer is characterized by highly aggressive clinical features, including liver metastases, bulky lymphadenopathy, and lytic bone metastases." (PMID 36439451, 2022). "Our investigations have revealed a novel consequence of potent activation of AR by MeT in prostate cancer cells." (PMID 36923279, 2022). "FLII contributed to growth of prostate cancer cells through AR-dependent signaling, and reintroducing FLII in CRPC cells sensitized the cells to endocrine therapies." (PMID 35756667, 2022). "Estrogen receptor α (ERα) and androgen receptor (AR) are nuclear hormone receptors essential for the regulation of cell differentiation, proliferation, and cell survival in breast cancer and prostate cancer." (PMID 35069908, 2022).
prostate carcinoma (continued). "We believe that this is due in part to metformin-induced decreases in AR activity, for expression of PPARγ and GR is suppressed by AR in human prostate cancer cells." (PMID 36175875, 2022). "Subsequently, Hwang group reported a new series of AR degraders for the treatment of metastatic castration-resistant prostate cancer." (PMID 35680848, 2022). "It has been proven that AR in prostate cancer cells promotes glycolysis and pyruvate oxidation, participates in fatty acid (FA) synthesis and oxidation, and regulates amino acid catabolism by increasing the expression of their transporters." (PMID 36361793, 2022). "Prostate cancer (PCa) growth and progression are uniquely dependent on androgens, making the androgen receptor pathway a prime target for therapy; however, cancer progression to androgen independence leads to treatment failure and poor prognosis." (PMID 35668070, 2022). "Androgen activates the androgen receptor which is critical for survival and proliferation of androgen-sensitive prostate cancer cells." (PMID 35454866, 2022). "AR is a critical regulator of DDR in prostate cancer, through regulation of the expression and activity of DNAPK." (PMID 36010882, 2022). "This is the first study to report that TR3 is a multifunctional regulator of AR signaling in prostate cancer cells." (PMID 35454821, 2022). "Although beyond the scope of this review, AR amplifications themselves have been shown to influence the AR cistrome in prostate cancer settings." (PMID 36212399, 2022). "We previously performed a large-scale screen to identify genes involved in ADT and ART resistance through overexpression of 17,255 open reading frames (ORFs) in LNCaP cells, an AR-dependent prostate cancer cell line." (PMID 35550030, 2022). "The relative expression of AR was 20% higher in patients with prostate cancer, which suggests its potential as a biomarker for prostate malignancy." (PMID 35456428, 2022). "TLE5 directly interacts with AR and prevents AR from binding DNA, thus suppressing ligand-dependent AR target gene expression and inhibiting prostate cancer progression and metastasis." (PMID 36438567, 2022). "The androgen receptor (AR) plays an essential role in prostate cancer progression and is a key target for prostate cancer treatment." (PMID 36446767, 2022). "We have previously reported dual transcriptional activities between constitutively active AR and wild‐type AR (AR‐WT) in prostate cancer." (PMID 34919781, 2022). "Here, by using a synthetic and highly potent androgen, MeT, we provide new insights into the consequences of hyperactivation of AR in prostate cancer." (PMID 36923279, 2022). "The dysregulation of the AR signaling in prostate cancer cells results in the over-expression of SRC and enhancement of metastatic ability of these cells." (PMID 34831421, 2021). "The AR‐regulated PCAL7 was abundantly overexpressed in prostate cancer tissues and AR‐dependent cell lines." (PMID 33219721, 2021). "Many prostate cancers express androgen receptor (AR), and, because of this, androgen deprivation therapy (ADT), which inhibits AR, is the standard medication for prostate cancer treatment." (PMID 34445235, 2021). "On the contrary, Tip60 promotes prostate cancer progression via acetylation of androgen receptor (AR) to augment AR signaling." (PMID 34880761, 2021). "Our integrative analysis of these data reveals known prostate cancer specific driver genes, such as AR and HOXB13, as well as a number of top hits that are poorly characterized." (PMID 34326322, 2021). "Prostate cancers are androgen receptor (AR)-dependent in the early stage and can thus be treated effectively through androgen blockade." (PMID 34476012, 2021). "ZBTB16 is a classic androgen receptor (AR) regulatory gene, which has antiproliferative activity in prostate cancer cells and plays a role in inhibiting cancer by inhibiting the MAPK pathway." (PMID 34660783, 2021).
prostate carcinoma (continued). "Strikingly, in prostate cancer, expression of AR-V7 is considered as a marker limiting treatment or predicting poor prognosis or as a constitutively active replacement for AR." (PMID 34440475, 2021). "We previously found that EWS plays an important role in prostate cancer, therefore we investigated the relationship between EWSR1 expression and AR expression, as AR is essential for prostate cancer development and progression." (PMID 34409300, 2021). "In prostate cancer, the androgen receptor (AR) pathway is one of the most important pathways implicated in disease progression and resistance to treatment and is therefore targeted by androgen deprivation therapy and hormone therapy." (PMID 33289351, 2021). "The function of hsa-miR-32 in NED was discovered in the context of inhibited AR signalling, resulting from the interaction of prostate cancer cells with mast cells, or from anti-androgen therapy." (PMID 34940756, 2021). "In support of this insight, previous data have shown that STAT3 activation enhances its interaction with the AR N-terminal domain in prostate cancer cells stimulated with the adipokine IL-6." (PMID 34066328, 2021). "TMPRSS2 is a well-known transcriptional target of AR in prostate cancer cells, and has recently been shown to be regulated by androgens and anti-androgens also in lung cells and mouse lung tissue." (PMID 34328182, 2021). "For example, CBP (CREB binding protein) and p300, both histone acetyl transferases (HATs), are known AR co-regulators that are overexpressed in prostate cancer." (PMID 33513133, 2021). "Enzalutamide or abiraterone have shown its effectiveness for prostate cancer patients, and novel targets other than AR itself are strongly required for combinatorial therapy." (PMID 33219721, 2021). "Proliferation and survival of prostate cancer cells are driven by the androgen receptor (AR) upon binding to androgen steroid hormones." (PMID 34434533, 2021). "In this study, we demonstrate the potential of computational analysis using publicly available transcriptional datasets to identify novel metabolic targets of AR in prostate cancer." (PMID 34503116, 2021). "BRG1 is required to drive the expression of numerous prostate cancer specific genes in an AR/FOXA1 dependant manner, but also works independently to drive the expression of pro-proliferative and DNA replication genes." (PMID 33596994, 2021). "Our previous studies demonstrated that kavalactones inhibited mRNA expression of PSA and TMPRESS2, two key AR target genes, in LNCaP cells and tumor tissues of prostate cancer PDX model." (PMID 34368644, 2021). "As such, androgen deprivation therapy (ADT) blocks the activation of AR and is used for the treatment of prostate cancer." (PMID 33671134, 2021). "In particular, analog #7 (ARVib-7) has better bioavailability than niclosamide and can inhibit prostate cancer cell proliferation and AR transcriptional activity." (PMID 34272475, 2021). "This is consistent with the well-established role of FOXA1 as a major AR co-regulator and pioneer factor in prostate cancer cells, and the emerging role of FOXM1 in this capacity as well." (PMID 33513133, 2021). "SOX9 transcription factor also impacts β-catenin and androgen receptor, leading to invasive prostate cancer." (PMID 35201496, 2021). "Therapeutic strategies for metastatic castration-resistant prostate cancer aim to target androgen receptor signaling." (PMID 34204608, 2021). "In fact, it is known that most of prostate cancers, including those apparently independent on hormone for growth, express significant amounts of AR." (PMID 35011576, 2021).
prostate carcinoma (continued). "LAT3 transcription was activated by androgen receptor (AR) signaling and then lead to leucine uptake, mTORC1 signaling, and cell proliferation in primary prostate cancer." (PMID 34503187, 2021). "We also realized that a mechanistic study is needed to verify the importance of those altered gene expression in prostate cancer progression, especially during the anti-AR treatment-induced neuroendocrinal evolution in CRPC patients." (PMID 34572596, 2021). "The enrichment term “Prostate cancer” with 10/97 genes, “miRNA regulation of prostate cancer signaling pathways” with 8/33 genes, and “Androgen receptor” (12/90) are also among the most changed enrichment terms confirming the specificity of the results." (PMID 34209195, 2021). "The signaling of the androgen receptor (AR) axis plays an essential role in prostate cancer development and progression." (PMID 33500577, 2021). "We found that AR, the main regulator of prostate cancer (PCa), played a pivotal role in NB proliferation consistent with our previous findings." (PMID 34041015, 2021). "Unlike the GEM models, which retain an intact mouse immune system, xenografted human prostate cancer cell lines usually produce relative structureless tumors, some of which retain expression of human AR protein." (PMID 33477370, 2021). "Androgen receptor (AR) mRNA expression was increased after DON treatment in prostate cancer cell lines PC-3, DU-145 and LNCaP." (PMID 34678978, 2021). "In PCa (prostate cancer), abnormal splicing of the androgen receptor pre-mRNA produces splicing isoforms that promote drug resistance and cancer aggression." (PMID 33407694, 2021). "There have been reports of aberrant MAPK/ERK function in advanced prostate cancer with enhanced AR signaling, but overall its role in prostate cancer requires further study." (PMID 33599076, 2021). "Jazz90 and Jazz167 are more cytotoxic against AR-null prostate cancer cells (PC3 and DU145) compared to normal prostate epithelial cells (PNT1A)." (PMID 33572730, 2021). "For instance, deregulated dynamics of KATs or KDACs on the androgen receptor (AR) target gene promoters escalate anti-androgen resistance, which leads to the growth and metastasis of prostate cancer (PCa) cells." (PMID 33803759, 2021). "Ligand-independent and synergistic activation of the AR by IL-6 is an important mechanism that contributes to prostate cancer progression." (PMID 34204596, 2021). "The androgen and AR signalling pathway is well known for its contribution to the progression of prostate cancer (PCa), and androgen deprivation therapy (ADT) is a first‐line treatment for advanced PCa." (PMID 33797847, 2021). "Substantial researches demonstrate that the androgen receptor (AR) signal pathway is the most important regulatory mechanism governing the malignant progression of prostate cancer (PCa)." (PMID 34413914, 2021). "AR gene markers were also detected through RNA-Seq and ddPCR analysis of prostate cancer CTCs taken from stabilized whole blood days after CTC-iChip sample extraction." (PMID 33802356, 2021). "Androgen receptor is also impacted by several miRNAs, which lead to up or downregulation of prostate cancer, which indirectly influences the Wnt/β-catenin axis." (PMID 35201496, 2021). "Recently, Chakravarthi and colleagues identified a fusion occurring in around 30% of primary prostate cancer cases and involving the AR target gene KLK4 as a 5′ partner and the non-coding pseudogene KLKP1." (PMID 33634124, 2021). "The mechanisms of ASC-J9 against prostate cancer have been deeply studied, which can be divided into the AR-dependent pathway and the AR-independent pathway." (PMID 34295247, 2021). "Androgen deprivation therapy (ADT) and androgen receptor (AR)-targeted therapy are the gold standard options for treating prostate cancer (PCa)." (PMID 34681745, 2021). "We tested the effect of androgens on the composition of S‐EVs subpopulations secreted by AR expressing prostate cancer cells." (PMID 34434533, 2021).
prostate carcinoma (continued). "AR target gene transcription, mediated by androgen, can promote the proliferation, differentiation, and metastasis of prostate cancer cells." (PMID 35342388, 2021). "MiR-541 is another oncogenic miRNA that can affect prostate cancer course through modulation of AR signaling." (PMID 34831421, 2021). "The role of androgen receptor signaling in prostate cancer progression is multilayered and has been extensively studied." (PMID 34209195, 2021). "Androgen receptor (AR) is an important target for many diseases including prostate cancer, hypogonadism, muscle wasting, osteoporosis, and benign prostate hyperplasia." (PMID 33778009, 2021). "Androgen receptor (AR) is a main driver of prostate cancer (PCa) growth and progression as well as the key drug target." (PMID 33810413, 2021). "Although the castration treatment with androgen receptor (AR) antagonist is an effective therapeutic approach for prostate cancer, many patients become marked resistance to treatment and further progressed to castration-resistant disease (CRPC)." (PMID 34353330, 2021). "Overall, the expression of prostate cancer markers AR, PSA, and PSMA was heterogeneous, as demonstrated by the unsupervised clustering." (PMID 33801459, 2021). "KDM4C knockdown significantly reduced proliferation, colony formation, AR transcriptional activity in prostate cancer cells and inhibited tumor growth of a prostate cancer model in zebrafish." (PMID 34220955, 2021). "Insulin-like growth factor (IGF) induces androgen receptor signaling via β-catenin, leading to the proliferation of prostate cancer." (PMID 35201496, 2021). "Alterations to the androgen receptor (AR) signalling axis and cellular metabolism are hallmarks of prostate cancer." (PMID 34382934, 2021). "The crosstalk between IFN and androgen signaling appears to be bidirectional given that IFN can induce Dtx3L/Parp9, and AR can repress IFN signaling through induction of genes such as SOCS3 in prostate cancer cells." (PMID 33976187, 2021). "For example, LncRNA LBCS suppresses castration resistance and proliferation of prostate cancer by functioning as a scaffold for hnRNPK protein and AR mRNA to inhibit AR translation efficiency." (PMID 33643926, 2021). "First, we set out to define the gene signature that would best illustrate the activation status of AR in prostate cancer." (PMID 34503116, 2021). "The angiocrine factor CCL5 promotes the downregulation of the androgen receptor (AR) in tumor cells, which accelerates the disassembly of focal adhesions, enhancing prostate cancer invasion." (PMID 34073394, 2021). "Ligand-independent AR phosphorylation and the subsequent activation, seen primarily in prostate cancers and breast and other cancer types, can be achieved through several RTKs, including EGFR family members." (PMID 34681618, 2021). "Disruptions of the AR pathway consist of AR point mutations, affecting both NTD and LBD, truncated variants, and gene amplifications, all of which confer selective advantage to prostate cancer cells with different mechanisms." (PMID 34638258, 2021). "Dysregulation of apoptosis through abnormal AR signaling is involved in prostate cancer development in LNCaP." (PMID 34298624, 2021). "In this study, enzalutamide showed a favorable safety profile, consistent with that seen in men with prostate cancer and women with AR-expressing, triple-negative breast cancer." (PMID 33591468, 2021). "For example, USP14 interacts with androgen receptor (AR) to regulate the progression in prostate cancer and breast cancer." (PMID 33771975, 2021). "miRNAs have been found to regulate key driving pathways in prostate cancer, such as the AR signaling axis, TMPRSS2-ERG, and PTEN20–23." (PMID 34031488, 2021). "In this model, an androgen receptor (AR)-positive and androgen-dependent (AD) mouse prostate cancer cell line, Myc-CaP, which was isolated from a c-Myc transgenic mouse prostate cancer, was employed." (PMID 34587977, 2021).